IL2 (interleukin 2)
Diseases named in the same sentence as IL2 in open-access papers (continued):
Sharing a sentence is not in itself a finding about the gene and the disease.
cancer (continued). "Other forms of cancer immunotherapy include cytokines that can regulate the host immune response, such as interleukin -2 (IL-2) and interferons (IFNs)." (PMID 36686754, 2022). "If we use IL-2, IL-4, and IL-12 as the adjuvant in cancer vaccine therapy, we need them to activate effector T cells." (PMID 35967400, 2022). "Some cytokines including GM-CSF, IFN-α, IL-2, IL-7, IL-12, IL-15, IL-18, and IL-21 have antitumor activity via stimulating immunity, inhibiting proliferation, or inducing apoptosis in cancer cells." (PMID 35062949, 2022). "We analyzed the cell viability and extent of H5 fluorescence staining in E0771 cancer cells that had been incubated with AZD5363 as well as in CD8+ T cell plus E0771 cell co-cultures that were incubated with IL-2 only or IL-2 plus AZD5363." (PMID 35501326, 2022). "Both CSF and IL-2 promote the proliferation and differentiation of immune cells, and consequently can be used to enhance anti-cancer immunity." (PMID 36297474, 2022). "Our analysis identified pathways in cancer and IL-2 signaling pathways as the most significantly affected by the all analyzed miRNAs." (PMID 35596173, 2022). "Multiple common gamma chain cytokines, including IL-2, IL-7, IL-15, and IL-21, have been used to enhance cancer vaccine." (PMID 35651800, 2022). "It is reported that part of the limitation in IL-2 efficacy for cancer treatment is related to IL-2-driven expansion of Tregs, which leads to a reduced antitumor immunity." (PMID 35213635, 2022). "The systemic inflammatory response of cancer prompts neutrophil infiltration, resulting in the secretion of interleukin-2 (IL-2), interleukin-6 (IL-6), interleukin-10 (IL-10), tumor necrosis factor α (TNF-α), and vascular endothelial growth factor (VEGF)." (PMID 35407463, 2022). "In this study, we investigated the use of bacteria therapy, namely, SL7207, in combination with Alb-IL2 immunotherapy as a novel approach for the treatment of cancer." (PMID 35962391, 2022). "Bempegaldesleukin is an investigational PEGylated IL-2 that is being evaluated, in combination with nivolumab, in the management of a variety of cancers." (PMID 35852114, 2022). "When the IL2-Smurf2 chimeric protein enters cancer cells in a dose- and time-dependent manner, it creates a large number of downstream degradation processes, which lead to apoptotic cell death." (PMID 36612252, 2022). "Researchers have used orthogonal IL-2 cytokines to transmit natural IL-2 This allows for the selective production of desired T cell subsets that hold promise in the cell therapy of cancer." (PMID 36275738, 2022). "Initial endeavors to procure IL2 from natural sources as a treatment for patients with cancer were disappointing." (PMID 36923304, 2022). "In this regard, several years ago, we tested the efficacy of a combination treatment with immunotherapy (recombinant IL-2), anti-inflammatory agent (medroxyprogesterone acetate), and antioxidants in patients with advanced cancer." (PMID 35742933, 2022). "Notable increases in the fold change of circulating levels of IL-2, IL-15, and IL-18 were also documented following SBRT and immunotherapy; these cytokines have been associated with promising cancer immunotherapeutic approaches." (PMID 35055015, 2022). "We show that Vγ9Vδ2 T cells, expanded in vitro with zoledronic acid (Zometa or ZOL) and Interleukin-2 (IL-2), are efficient cancer cell killers with a trend towards increased killing efficacy after prolonged expansion time." (PMID 34149689, 2021). "This compelling evidence supports further studies to evaluate CIMVs-IL2 effectiveness, using cancer mouse models with a reconstituted human immune system." (PMID 33579033, 2021). "Interleukin 2 (IL2) was one of the first cytokines used for cancer treatment due to its ability to stimulate anti-cancer immunity." (PMID 33579033, 2021).
cancer (continued). "In patients with cancer treated with cytokines (e.g. IL-2, IL-2 +IFNα, and IFNα), 50% of subjects developed mild depressive symptomology and 22% developed moderate to marked depressive symptomology." (PMID 34429399, 2021). "Another approach using MSCs as delivery vehicles is the engineered expression of IL2, a cytokine frequently used in cancer therapy due to its stimulatory effect on CD8+ T cells and NK cells." (PMID 33668854, 2021). "The inflammatory response from cancer cells promotes the infiltration of neutrophils, which benefits cancer progression via the secretion of IL-2, IL-6, IL-10, TNFα, and VEGF." (PMID 34503128, 2021). "Broader therapeutic use of IL-2 and other costimulatory axes in cancer will likely require focusing their effects on those T cells which stand to deliver the greatest therapeutic effect, in particular cancer AgS T cells." (PMID 34584159, 2021). "The adjuvants co-administered with cancer vaccines tested in clinical trials and named in this review are GM-CSF, Il-2, MIS416, poly-ICL, Montanide ISA-51, CHP and ISCOMATRIX and AS15." (PMID 34065557, 2021). "This ultimately led to FDA approval in 1992 for the treatment of metastatic renal cell carcinoma, making IL-2 the first cancer immunotherapy in humans." (PMID 34200997, 2021). "Other studies show that addition of adjuvants to vaccine administration, as IL-2 and GM-CSF, heat shock proteins and radiation can improve the immune response against cancer in the host and increase the overall survival." (PMID 33902630, 2021). "On the other hand, due to Treg activation by IL-2 and its dose adjustment complications in cancer treatment, some studies have shown that T cell depletion is more effective than neutralization of IL-2 in PC." (PMID 34868907, 2021). "This section discusses existing IL-2-based strategies for cancer immunotherapy that have emerged in an attempt to circumvent the shortcomings and improve efficacy compared to the original high-dose strategy." (PMID 34790830, 2021). "Coupling the TNC specific F16 antibody to IL-2 (Teleukin®) was used to deliver IL-2 into the cancer tissue." (PMID 33790905, 2021). "Together, these results demonstrate that the bispecific antibody is a safe and effective IL-2R agonist that harnesses the benefits of the IL-2 signaling pathway as a potential anti-cancer therapy." (PMID 34011961, 2021). "Although modest success is observed in the clinic, cancer patients receiving IL-2 therapy experience a wide array of side effects ranging from flu-like symptoms to life-threatening conditions such as vascular leak syndrome." (PMID 34790830, 2021). "Since the last century, bacillus Calmette–Guerin vaccine, interferon-alpha, and interleukin-2 (IL-2) have been used for immunotherapy of cancer." (PMID 33968730, 2021). "Both TIL-iPS-T and TI-CTL slightly produced interferon-γ (INF-γ) and tumor necrosis factor (TNF), but hardly IL-2, in response to co-culturing with cancer spheroids." (PMID 34099861, 2021). "Specifically, inspired by earlier work on IL2-enhanced ACT for cancer therapy, we showed that recombinant IL2 administered in 12-hour intervals resulted in enhanced antiviral protection equivalent to daily doublings of the effector cell population." (PMID 34489940, 2021). "During the last two decades, several attempts to enhance NK cell functions as a therapy for the treatment of AML or other cancers have been tested including the stimulation in vitro or in vivo by γc cytokines (IL-2, IL-15, IL-21, etc.)." (PMID 34975835, 2021). "In conclusion, the use of CIMVs-IL2 has the potential to provide a more effective anti-cancer therapy." (PMID 33579033, 2021). "In vitro culture of peripheral blood mononuclear cells (PBMCs) with interleukin-2 (IL-2) for several days results in a population of LAK cells with upregulated cytotoxicity against cancer cells and IFN-γ production." (PMID 34234868, 2021).
cancer (continued). "In our study, we documented that in the memory-like NK cells from healthy donors and cancer patients, there is an increase in the expression of the NCRs, NKp30, NKp44 and NKp46 superior to that induced by treatment with IL-2 alone in the control NK cells." (PMID 33808051, 2021). "IL-2 has been approved for the treatment of metastatic melanoma and renal cancer since its use in cancer therapy in 1984 to date patients." (PMID 34869005, 2021). "Although adoptive cell therapy (ACT) using TILs resulted in regression of cancer for several months, the treatment with IL-2 led to toxic side effects." (PMID 33807011, 2021). "Targets other than TAAs expressed on the cancer cells have been explored for IL-2 immunocytokine therapy." (PMID 33803078, 2021). "IL-15 belongs to the IL-2 cytokine family; however, in a previous study, IL-15 was shown to have a wider range of therapeutic effects with fewer side effect compared to those of IL-2, making IL-15 a good candidate for cancer treatment." (PMID 33912464, 2021). "The results of PPI demonstrated that the five TFs were tightly associated with many critical cancer related factors or pathways, such as SMAD4, MMP13, IL-5, IL-2, CYP2E1, CCNE1 and CDH1." (PMID 34405021, 2021). "Although IL-2 is utilized in a wide variety of settings, we have chosen to specifically discuss IL-2-based fusion proteins used in a cancer therapeutic setting." (PMID 34790830, 2021). "IL-15 was discovered as a molecule highly related to interleukin-2 (IL-2), which reached the clinical setting as an approved biological drug in 1992 and was the first paradigm of successful immunotherapy of cancer." (PMID 33671252, 2021). "We describe that Vγ9Vδ2 T cells expanded with ZOL and IL-2 are capable of killing cancer cells as well as cross-presenting tumor antigens." (PMID 34149689, 2021). "Since then, IL-2 and other cytokines have extensively been studied as vaccine adjuvants in both infectious and cancer scenarios." (PMID 34065557, 2021). "Promotion of IL-2 production was the first immune regimen approved for cancer therapy and currently mediates immunomodulation by activating IL-2 receptor trimers (CD25, CD132 and CD122) and dimers (CD132 and CD122)." (PMID 34869005, 2021). "Our group has previously shown that therapeutic index and anti-cancer activity of potent cytokines such as IL-2, IL-12 or TNF, can be improved by fusing them to the L19 antibody in various formats." (PMID 34576184, 2021). "Although clinical response rates were modest, they laid the groundwork for the development of IL-2-based immunotherapies for cancer treatment." (PMID 34790830, 2021). "The cytokine IL-2 is critical for T cell proliferation and has shown antitumor activity in both preclinical models and in patients with cancer." (PMID 34771735, 2021). "IL-2 is useful for expanding effector T cells in cancer therapy, however, it is also found to expand Treg cells in low-42 and high dose." (PMID 33723260, 2021). "An early clinical study reported atherosclerotic CVE in 3.8% (angina or ischemic changes in 2.6% and myocardial infarction in 1.2%) of patients who received IL-2 for cancer therapy." (PMID 35097027, 2021). "Human interleukin-2 (iL-2), used in different cancers therapies, was successfully expressed in Ch. reinhardtii and Dunaliella salina producing about 0.94% and 0.59% of iL-2 respectively." (PMID 34451730, 2021). "At the same time, factors that are well-recognized as immunosuppressive and cancer growth-inhibiting (i.e., IL-2 and IL-9) were downregulated (<−0.5 log of change)." (PMID 34771587, 2021). "The application of IL-2 in tumor therapy has confirmed the effectiveness of adaptive immunity for cancer control and revealed T-cell regulation as a new strategy for immunotherapy." (PMID 33968730, 2021). "The contrasting actions of IL-2 has led to inconsistent responses and limited the development of high-dose IL-2 for cancer immunotherapy." (PMID 33654071, 2021).
cancer (continued). "Upon encountering the cancer cells, cytotoxic T cells further proliferate and exhibit an enhanced level of activity by producing IL-2 and IFNγ, while regulatory T cells negatively modulate their activity by inducing their exhaustion." (PMID 34359653, 2021). "Systemic IL-2 administration has had a long history of high regression rates in patients with various advanced cancers." (PMID 34553029, 2021). "Then, we used interleukin-2 (IL-2)-treated NK cells from cancer patients and healthy individuals as effectors to target tumors in the absence and presence of anti-MICA/B monoclonal antibodies (mAbs)." (PMID 33440654, 2021). "The effectiveness of the use of CIMVs-IL2 remains to be proven in humanised cancer mouse models with reconstituted human immune system, as the next step to realising the clinical potential of therapeutic CIMVs." (PMID 33579033, 2021). "In conclusion, IL-2 has been a cornerstone of cancer immunotherapy because of its critical role in the T cell activation pathway." (PMID 34790830, 2021). "In terms of cancer research, different case-control studies have suggested the association of IL1A, IL2, and IL6 with CRC." (PMID 34931923, 2021). "IL-2 was the first cytokine to be successfully used in the treatment of cancer to induce T cell activation." (PMID 33654071, 2021). "IL-2 became one of the first candidates for cancer immunotherapy following its discovery as a key factor for T cell functioning." (PMID 34790830, 2021). "Phenotypically, we notice abundant cell surface PD-L1 in HuR-high cancer cells, which significantly inhibits immune activation of co-cultured T cells as indicated by IL-2 production." (PMID 33649535, 2021). "Engaging the immune system in the fight against cancer has been firmly established, with Interleukin-2 (IL-2) being one of the first recombinant proteins to be successfully used as a treatment for cancer nearly 40 years ago1,2." (PMID 34011961, 2021). "Accordingly, the adoptive transfer of heterologous NK cells showed the killing of both differentiated and undifferentiated cancer cells upon activation with IL-2 and IL-15 in various cancer models." (PMID 34572009, 2021). "IL‐2 is an essential immunomodulatory cytokine that reflects cellular immunity; thus, an increase in IL‐2 level suggests the enhancement of cellular immunity in patients with cancer." (PMID 34302428, 2021). "Since IL-2 had been applied in cancer immunotherapy clinically, it is worth testing the utility of IL-2 in CRC patients with CSF1R c.1085 genotype A_A." (PMID 34830445, 2021). "Interleukin 2 (IL-2) plays a fundamental role in both immune activation and tolerance and has revolutionized the field of cancer immunotherapy since its discovery." (PMID 34790830, 2021). "Analysis of the CD4+ T cell compartment in cancer patients showed expansion of CD25+ FoxP3+ Tregs following IL-2 therapy." (PMID 34790830, 2021). "Previous clinical studies showed that CBSM led to positive psychosocial and physiological changes (lower cortisol and higher interleukin-2 and interferon-γ levels in serum) in stressed cancer patients." (PMID 34830968, 2021). "IL-2 is the first cytokine approved for use in patients owing to its promising ability to activate anti-cancer immunity and stimulate the production of lymphokine-activated killer cells." (PMID 34439285, 2021). "Recombinant human interleukin 2 (IL-2), also known as aldesleukin, was the first immunomodulatory protein approved for cancer treatment." (PMID 34084172, 2021). "Utilizing distinct mechanisms of NK cells will be critical to have synergistic effects in combination with other cancer therapies, including chemotherapy, immune-modulating cytokines (IL-2 and IFN-γ) therapy, and immune checkpoint blockades immunotherapy." (PMID 33918941, 2021). "For instance, IL-2 is the first effective immunotherapy of human cancer but it is also known to be very toxic." (PMID 32292786, 2020).
cancer (continued). "Some cancer patients have high levels of soluble IL2Ra in their serum, with a significant fraction bound to IL2." (PMID 33066142, 2020). "The production of IL-2 decorated particles for cancer therapy must follow the principles described here." (PMID 32917054, 2020). "Previously reported data also shows that IL2 can directly inhibit cancer cell growth in vivo and in vitro." (PMID 32560387, 2020). "Currently, IL2 has found its place in cancer immunotherapy for the expansion of immune cells such as NK cells, T-cells, NKT-cells, cytokine-induced killer (CIK) cells." (PMID 32582698, 2020). "This clearly demonstrated a superiority of IL-2/IL-15-expanded cells over IL-2-expanded cells in terms of cytotoxicity against a variety of cancer cells." (PMID 32983105, 2020). "Here, we summarize the current knowledge about the biology and function of IL-2, IL-15 and their receptor systems, with further discussion on clinical applications of these two cytokines for cancer treatment." (PMID 33266177, 2020). "It has long been recognized that doxorubicin increases the therapeutic potential of IL-12, TNF-α, and IL-2 in animal models of cancer." (PMID 32340275, 2020). "While it was a popular and promising treatment with IL-2 and interferon and cancer vaccines in the 1980s, it later lost its popularity." (PMID 32512674, 2020). "We were able to quantify the phosphorylation of these signaling molecules in response to IL-2/12 stimulation in both healthy donors and cancer patients." (PMID 32508837, 2020). "While its use in cancer therapy was high-dose, it was subsequently recognized that low doses of IL-2 preferentially expand tolerance-inducing regulatory T cells." (PMID 32917054, 2020). "IFNα and IL-2 represent the first recombinant cytokines approved for cancer immunotherapy; however, others, such as IL-7 and IL-15, are under clinical investigation." (PMID 32823961, 2020). "The anti-cancer drugs actinomycin D and cisplatin and a representative immunosuppressive drug, azathioprine, also significantly suppressed IL-2 LA." (PMID 32200032, 2020). "Although IL-2 stimulates immune responses directed at cancer cells, it also suppresses immune responses by maintenance of CD25+ Foxp3 T-regulatory cells and by participation in AICD." (PMID 32508818, 2020). "These strategies range from inhibition of IL‐2 to achieve immunosuppression, to the application of IL‐2 as a vaccine adjuvant and in cancer therapies." (PMID 32480431, 2020). "Considerable effort was invested in using IL-2 as therapeutic agent for a variety of diseases, ranging from autoimmune and inflammatory disorders, allograft rejection, to cancer." (PMID 32917054, 2020). "NeoleukinTM-2/15 cancer treatments have also been shown to increase the CD8+: Treg suggesting a mechanism similar to IL2 and IL15." (PMID 33216834, 2020). "High-dose recombinant human IL-2 (aldesleukin) was originally approved as a cancer immunotherapy due to its stimulatory activity on cancer-killing effector CD4+ and CD8+ T cells and NK cells." (PMID 32411127, 2020). "It is the ability of IL2 to stimulate the proliferation and activation of immune cells with antitumor activity that made it possible to achieve successes in IL2-based immunotherapy of cancer." (PMID 32560387, 2020). "The emergence of cancer immunotherapy continued until the FDA-approved Interleukin-2 and the first monoclonal antibody (mAbs), Rituximab were used as anti-cancer therapies in 1992 and 1997, respectively." (PMID 33042104, 2020). "Here, we discuss recent clinical and preclinical advances of IL-2- or IL-15-based immunotherapy in cancer patients." (PMID 33266177, 2020). "Other members in the IL2 cytokine family play a similar and synergistic role with IL2 in cancer immunity through a shared gamma chain (CD132) in their receptor and downstream JAK-STAT signaling." (PMID 33381115, 2020).